TWIST1 (twist family bHLH transcription factor 1)
Diseases named in the same sentence as TWIST1 in open-access papers (continued):
Sharing a sentence is not in itself a finding about the gene and the disease.
renal fibrosis (continued). "Besides its chemotactic capacity, the MCP-1/CCR2 axis has been associated with the transdifferentiation of macrophages to myofibroblasts in a model of Twist1-deficient mice with UUO in which the levels of MCP-1 and CCR2 and consequently renal fibrosis were reduced." (PMID 39450175, 2024). "Therefore, SirT1, STAT3, Twist1 and Cpt1a may represent useful targets for the prevention of renal fibrosis." (PMID 35408745, 2022). "TWIST1 PI polyamide may become a novel medicine for the treatment of renal fibrosis." (PMID 36018840, 2022). "The systemic administration of TWIST1 PI polyamide considerably improved renal fibrosis in UUO kidney, indicating that the TWIST1-C3 system is involved in renal fibrosis through the EMT phenomenon." (PMID 36018840, 2022). "In the present study, we investigated the contributions of TWIST1 to the upregulation of C3 in the EMT phenomenon and renal fibrosis in a mouse UUO model with PI polyamides targeting TWIST1." (PMID 36018840, 2022). "Twist1 is the key molecule that drives phenotypic changes in epithelial-mesenchymal transdifferentiation (i.e., EMT) in renal fibrosis and various tumors." (PMID 35664054, 2022). "We investigated roles of twist-related protein 1 (TWIST1) in EMT phenomenon and renal fibrosis through C3 upregulation in a mouse UUO model with gene silencer pyrrole-imidazole (PI) polyamides targeting TWIST1." (PMID 36018840, 2022). "TWIST1 induced the EMT phenomenon and renal fibrosis by upregulation of C3 with TGF-β1 in a mouse UUO model." (PMID 36018840, 2022). "Emerging evidences have shown that Snail and Twist1, the EMT transcription factors, play important roles in the pathogenesis of renal fibrosis." (PMID 33588892, 2021). "It was reported that conditional deletion of Twist1 or Snail in proximal tubular epithelial cells inhibited EMT, attenuated interstitial fibrosis in experimentally induced renal fibrosis in mouse." (PMID 33588892, 2021). "TGF-β1 is a key driver of renal fibrosis, and the expression of TGF-β1 promotes the development and progression of renal disease while also activating the expression of Twist1 or Snail to prolong G2/M arrest and promote renal fibrosis." (PMID 34769288, 2021). "Furthermore, we reported that Twist1 is highly expressed in HK2 cells and promotes renal fibrosis by regulating EMT." (PMID 35182235, 2022). "Furthermore, we observed that silenced Twist1 by siRNA alleviated the occurrence of EMT and the progression of renal fibrosis induced by AA, suggesting Twist1 plays an important role in AA-induced AKI-CKD transition." (PMID 33588892, 2021). "Additionally, Twist1 has been reported to induce EMT and renal fibrosis via the TGFβ pathway." (PMID 39897544, 2025). "The high expressions of TGF-β, Twist1 (transcription factor inducing EMT) and vimentin (fibroblast marker) in UUO rats further suggested that EMT may be one of the important mechanisms of UUO-induced renal fibrosis." (PMID 35408745, 2022). "We previously demonstrated that Twist1 is involved in hypoxia-induced EMT and contributes to fibrogenesis in renal tubular cells by HIF-1α activation, but it was still unclear whether downstream molecules regulated by Twist1 could promote renal fibrosis." (PMID 35182235, 2022). "Snail1 and Twist1, two markers of EMT, and MMP2, a marker of invasion and migration, which could degrade the extracellular matrix, were downregulated in TRIM6 knockdown CRC cells, which is consistent with a study on TRIM6 in renal fibrosis." (PMID 34589421, 2021). "However, a direct interaction between Notch/Hedgehog and Twist1 in renal fibrosis has not been found, and the hypothesis needs further investigation." (PMID 29314610, 2018).
endometrial cancer (20 papers, 2014 to 2025). Primary or metastatic malignant neoplasm involving the endometrium (mucous membrane that lines the endometrial cavity). "Previous studies have also found that SNHG25 can promote the malignancy of endometrial cancer through miRNA sponges, and it can affect the invasion and apoptosis of renal cancer cells by regulating the miR-363-3p-Twist1 interaction." (PMID 40894525, 2025). "In such a case, miR-214-3p repressed TWIST1 expression in endometrial cancer cells, which suppresses the EMT and metastasis." (PMID 38662258, 2024). "We have revealed that silencing of ZEB2 can effectively make endometrial cancer cells more sensitive to Paclitaxel treatment and lead to the downregulation of Twist1, MMP2, and vimentin and upregulation of E-cadherin." (PMID 35992812, 2022). "Consistently, upregulation of EMT-associated genes like TWIST1 and SNAI1 was demonstrated in an endometrial cancer stem-like cell line and treatment with EMT-blocker salinomycin inhibited the tumorigenicity of these cells." (PMID 35328833, 2022). "The correlation between expression of TWIST1 and the clinicopathological parameters in 263 cases with type I endometrial cancers." (PMID 33235117, 2020). "The aberrant expression of TWIST1 in 345 cases of type I endometrial cancers, atypical endometrial hyperplasia and normal endometrium." (PMID 33235117, 2020). "In endometrial cancer cells, miRNAs can activate or attenuate EMT and CSC by targeting PTEN and other EMT-associated genes, such as Twist1, ZEB1 and BMI-1." (PMID 25141911, 2014). "Furthermore, NOL6 is overexpressed in endometrial cancer and regulates TWIST1 expression, promotes migration, and reduces apoptosis." (PMID 37667226, 2023). "Furthermore, miR-101 has been shown to suppress EMT, self-renewal and invasiveness of aggressive endometrial cancer cells by decreasing the expression of TWIST1, ALDH1 and Nanog." (PMID 35328833, 2022). "Together, these data indicate that ISL might reverses EMT through a TGF-β1/Smad3/TWIST1/2 dependent signaling pathway in human endometrial cancer cells." (PMID 33799801, 2021). "Both preclinical studies demonstrate that ISL could inhibit TGF-β/Smad-induced endometrial cancer cell migration through reducing p-Smad2/3 and TWIST1/2 expression, subsequently decreasing N-cadherin, vimentin, α-SMA while increasing E-cadherin protein expression." (PMID 33799801, 2021). "Furthermore, miR-106b inhibited EMT by targeting Twist1 in invasive endometrial cancer cell lines." (PMID 25760076, 2015). "Taken together, our results constructed a circ_0007534/miR-625/ZEB2 signaling, which drives endometrial cancer progression and chemoresistance by modulating several key EMT-related genes, including Twist1, MMP2, E-cadherin, and Vimentin." (PMID 35992812, 2022). "Here, we demonstrated that in endometrial cancer cells both TET3 and OGT affected the expression of genes involved in epithelial to mesenchymal transition (EMT), i.e., FOXC1, TWIST1, and ZEB1." (PMID 34948036, 2021). "In conclusion, our results showed that both TET3 and OGT are involved in the regulation of FOXC1, TWIST1, and ZEB1 in endometrial cancer and affect cancer cell migration and invasion." (PMID 34948036, 2021). "miR-543 level decreased in endometrial cancer cells and inversely correlated with mRNA levels of FAK and Twist homolog 1 (TWIST1)." (PMID 27999452, 2016). "We showed significant abnormalities in the expression of cancer-promoting genes in tissues proximal to endometrial cancer, with higher expression of MYC, NR5A2, SNAI1, and TWIST1, in tumor-adjacent tissues than in tumors, which suggests field cancerization effect." (PMID 36140779, 2022). "The results of this study demonstrated that ISL could reverse TGF-β-induced endometrial cancer cell migration through inhibition of TGF-β/Smad signaling pathway with subsequent increased E-cadherin expression and reduced N-cadherin, vimentin, α-SMA, p-Smad3, and TWIST1/2 expression." (PMID 33799801, 2021).
liver cancer (20 papers, 2015 to 2025). An epithelial or non-epithelial malignant neoplasm that arises from the liver. "For example, Wang LT and colleagues found that SPZ1 promoted EMT and metastasis in liver cancer, specifically by trans-activating TWIST1, which encodes a master regulator of EMT." (PMID 34749766, 2021). "LCN2/Twist1 signaling pathway was associated with liver cancer." (PMID 32272958, 2020). "One study highlights that lactate accumulation in the TME can drive the epithelial–mesenchymal transition (EMT) in liver cancer cells through the lactylation of twist family BHLH transcription factor 1 (TWIST1), a transcription factor critical for EMT." (PMID 40867622, 2025). "The protein level of Twist1 was significantly reduced by ADQ treatment in various liver cancer cell lines, including SK-Hep1, Huh7, and Hep3B." (PMID 34408201, 2021). "The decrease in p-Akt and Twist1 levels was also observed in other liver cancer cell lines, such as Hep3B and Huh7 cells." (PMID 34408201, 2021). "Both MYC and MYC/Twist1 mice were observed to develop multifocal liver cancer, while only MYC/Twist1 mice developed lung metastases." (PMID 31933479, 2020). "This hypothesis was supported by the finding that expression levels of SNAIL1 were significantly correlated with VIM (Vimentin) and TWIST1 in 423 liver cancer patients (TCGA liver cancer)." (PMID 30405889, 2018). "In liver cancer, KIFC1 activates the gankyrin/AKT/TWIST1 pathway, promoting epithelial-stromal transformation and metastasis." (PMID 40379626, 2025). "In liver cancer cells that secrete alpha-fetoprotein (AFP), miR-675 targets Twist1 and Rb1 to activate the expression of the epithelial marker gene CDH1 and inhibits the expression of the mesenchymal marker gene Vim to reduce the invasive ability of HCC and block EMT." (PMID 35805066, 2022). "Moreover, HBV infection has been considered as a driving force for EMT during liver cancer evolution, with remarkably elevated expressions of EMT markers including Snail Family Transcriptional Repressor 2 (SNAI2) and Twist Family BHLH Transcription Factor 1 (TWIST1) in infected liver organoids." (PMID 35541903, 2022).
head and neck squamous cell carcinoma (19 papers, 2011 to 2025). A squamous cell carcinoma that arises from any of the following anatomic sites: lip and oral cavity, nasal cavity, paranasal sinuses, pharynx, larynx, and salivary glands. "BMI1 was found to be regulated by Twist1 to promote EMT in head and neck squamous cell carcinoma (HNSCC)." (PMID 39598229, 2024). "In the present study, we have demonstrated the possible function of Twist1 in the chemosensitivity of head and neck squamous cell carcinoma (HNSCC) and have identified that its mechanism maybe associated with MDR1/P-gp regulation." (PMID 24805866, 2014). "Way T D reported that in head and neck squamous cell carcinoma (HNSCC), overexpression of TWIST1 upregulates β-catenin expression." (PMID 36123378, 2022). "Twist1 expression is upregulated in head and neck squamous cell carcinoma (HNSCC) cell lines treated with interleukin 6 (IL-6)." (PMID 33808323, 2021). "In head and neck squamous cell carcinoma (HNSCC), PRMT5-mediated H3R2me2s facilitates the recruitment of the MLL/SET1/WDR5 complex to the TWIST1 promoter, increasing H3K4me3 and TWIST1 transcription, thereby promoting EMT and lymph node metastasis." (PMID 41204384, 2025). "TWIST1 upregulates BMI1, a marker of CSCs that is essential for tumor initiation capacity in head and neck squamous cell carcinomas." (PMID 38555451, 2024). "For example, it was shown that BMI1, a component of PRC1, acted cooperatively with TWIST1, one of EMT-related transcription factors (EMT-TFs), to repress CDH1 during EMT in head and neck squamous cell carcinoma." (PMID 33779563, 2021). "TWIST1 upregulates BMI1, which is essential for promoting EMT and tumor-initiating capability, in head and neck squamous cell carcinoma." (PMID 34809669, 2021). "Here, we study the prognostic significance of TWIST1 and TWIST2 in Head and Neck squamous cell carcinoma (HNSCC) as well as interactions of TWISTs with both gender and smoking in patient survival." (PMID 29156759, 2017). "Similarly, in head and neck squamous cell carcinoma (HNSCC), the overexpression of the arginine methyltransferase PRMT5 resulted in increased Twist1 and N-cadherin levels, whilst E-cadherin levels decreased." (PMID 38827317, 2024). "Studies have found that vascular endothelial growth factor (VEGF) and insulin-like growth factor (IGF) secreted by vascular endothelial cells in head and neck squamous cell carcinoma promote EMT and metastasis of tumour cells via the VEGFR-2/HEF1/AKT/Twist1 pathway." (PMID 31205475, 2019). "In addition, co-expression of TWIST1, HIF-1α and SNAIL has been correlated with metastasis and poor prognosis in primary tumors of head and neck squamous cell carcinoma (HNSCC) patients." (PMID 23741524, 2013). "Similarly, the cooperation between Twist1 and BMI1 to suppress let-7i expression promoted the acquisition of properties of the EMT, namely cell migration and stem-like properties in head and neck squamous cell carcinoma (HNSCC)." (PMID 32353968, 2020).
lymph node metastasis (19 papers, 2011 to 2025). "In cancer, the expression of TWIST1 is associated with lymphatic vessel invasion, lymph node metastasis, and perineural invasion." (PMID 37513937, 2023). "Twist1 expression in stromal fibroblasts was associated with advanced pT stage (P = 0.007), lymph node metastasis (P = 0.030), and advanced clinical stage (P = 0.019)." (PMID 29029429, 2017). "As lymph node metastasis is highly associated with poor prognosis, we determined the association between the co-expression of TWIST1 and ZEB2 and patient survival in lymph node positive and negative patients separately." (PMID 26214683, 2015). "TWIST1 stromal cell staining was associated with adverse features like more advanced pT (p = 0.0044), lymph node metastasis (p = 0.0301), lymphatic vessel invasion (p = 0.0373), perineural invasion (p = 0.0109) and worse overall survival time (p = 0.0226)." (PMID 25528769, 2015). "A statistical association between high levels of TWIST1 in tumor tissues and lymph node metastasis (LNM) was observed (p = 0.016), while only a trend to statistical association was found for age (p = 0.052) and tumor stage (p = 0.07)." (PMID 21464926, 2011). "We found a statistically significant relationship between high expression of TWIST1 and lymph node metastasis (n = 24, P = .001)." (PMID 33235117, 2020). "More importantly, multivariate analysis showed that high TWIST1 expression, in addition to myometrial invasion, lymph vascular space invasion, and lymph node metastasis, was an independent predictor of worse DFS in patients with type I ECs." (PMID 33235117, 2020). "The expression levels of Bcl-2, Twist1, E-cadherin, N-cadherin, Vimentin and MMP-2/9 were significantly associated with lymph node metastasis, and the differences in the pathologic grades were significant." (PMID 28032603, 2017). "TWIST1 expression was restricted to tumor tissues (86.1%) and correlated with lymph node metastasis (LNM)." (PMID 21464926, 2011). "Besides, TWIST1 overexpression in CRC cells was associated with more advanced pT, lymph node metastasis, and worse survival." (PMID 34768901, 2021). "However, the correlation of TWIST1 expression levels with lymph node metastasis and stages remains controversial, since some studies highlighted a significant relationship, while others did not." (PMID 34768901, 2021). "The expression of Twist1 in stromal fibroblasts was observed in 89.9% of ESCC patients and positively associated with the increased depth of tumor invasion, lymph node metastasis, and advanced clinical stage, and a significant adverse prognostic factor in overall survival." (PMID 29029429, 2017). "Slug and Vimentin levels were significantly increased in patients with T-stage ≥ T3, while patients who had lymph node metastasis had significantly higher HAS-2, SNAI1, TWIST1, N-Cadh, Slug, and MMP-9." (PMID 40149256, 2025). "The significance of TWIST1 expression in CRC is still controversial, in a way that some studies have shown that expression level of TWIST1 is positively correlated with lymph node metastasis and stage among CRC cases." (PMID 33752711, 2021). "In the present study, we found that Twist1 expression in ESCC stromal fibroblasts was significantly related to advanced pT stage, lymph node metastasis, and advanced clinical stage." (PMID 29029429, 2017). "In detail, high expression of Twist1 was found in 63% (14 of 22) of NPC patients, in which 77.8% of patients with lymph node metastasis and 63% of patients with distance metastasis." (PMID 27793033, 2016). "High expression of the TWIST1-ceRNET components was significantly correlated with lymph node metastasis and advanced TNM staging (Lymph node metastasis: P = 0.025 for TWIST1, P = 0.005 for SLC12A5, P < 0.001 for ZFHX4; TNM stage: P = 0.008 for TWIST1, P = 0.015 for SLC12A5, P = 0.012 for ZFHX4;)." (PMID 31645542, 2019). "This analysis confirmed that TWIST1 expression levels have prognosis value only in patients without lymph node metastasis." (PMID 21464926, 2011).
lymph node metastasis (continued). "Notably, co-expression of TWIST1 and ZEB2 in OSCC was significantly associated with poorer overall survival, particularly in patients without detectable lymph node metastasis." (PMID 26214683, 2015). "Remarkably, co-expression of TWIST1 and ZEB2 was correlated with poorer overall survival in OSCC, particularly in patients with no lymph node metastasis." (PMID 34567183, 2021). "Notably, co-expression of TWIST1 and ZEB2 was significantly prevalent in OSCC patients with poorer overall survival particularly in patients with no lymph node metastasis." (PMID 26214683, 2015).